DUSP4 (dual specificity phosphatase 4)
Diseases named in the same sentence as DUSP4 in open-access papers (continued):
Sharing a sentence is not in itself a finding about the gene and the disease.
glioma (10 papers, 2014 to 2024). A benign or malignant brain and spinal cord tumor that arises from glial cells (astrocytes, oligodendrocytes, ependymal cells). "In glioma patients, DUSP4 expression correlates with the GFAPδ/α ratio, and high expression is associated with worse prognosis." (PMID 35372061, 2022). "DUSP4 expression in glioma correlates with the GFAPδ/α ratio, and high expression is associated with a worse prognosis.LAMA1 associated with gliomas invasion was increased in cells with a high GFAPδ expression compared to GFAPα." (PMID 35372061, 2022). "In gliomas, mutations in the MAPK pathway and constitutive activation of the DUSP4 that target ERK and Janus kinase (JNK) are common." (PMID 35372061, 2022). "Two additional studies suggest that DUSP-4 may be a diagnostic and prognostic marker for IDH1 mutant gliomas, GNA12 signaling regulation promotes transcriptional and phenotypic responses to GBM tumor invasion." (PMID 39830513, 2024). "Moreover, DUSP4 activity influences key biological process dysregulated in gliomas like cell migration, invasion, proliferation, ECM degradation, and chemotherapy-induced cytotoxicity." (PMID 35372061, 2022). "Therefore, concerning cell–ECM interaction pathways changed by DUSP4 status, van Bodegraven and colleagues show that a high GFAPδ/α ratio enables glioma cells to have a greater invasiveness capability in the brain." (PMID 35372061, 2022). "Accordingly, the DUSP4 expression level might serve as a predictor of IDH1 mutation, which currently is crucial for the molecular diagnosis of gliomas." (PMID 30791455, 2019). "Therefore, downregulation of DUSP4 expression in gliomas is suggested to be caused by epigenetic regulation triggered by IDH1 mutation and to contribute to glioma tumorigenesis through enhancement of MAPK signaling." (PMID 30791455, 2019). "From previous studies, DUSP4 and BMP7 are known to be methylated in gliomas and gastric- and prostate cancer, respectively." (PMID 25226156, 2014). "In glioma cells, changes in Glial Fibrillary Acidic Protein (GFAP) can affect the invasiveness of glioma cells by affecting the expression of the Dual-Specificity Phosphatase 4 (DUSP4) in focal adhesions." (PMID 33614284, 2021).
lung cancer (9 papers, 2014 to 2024). A malignant neoplasm involving the lung. "These T cells appeared to resemble a recently described IL7R-HAVCR2+KRT86+DUSP4+LAYN+ subset, which has been associated with response to anti-PD1 therapy in lung cancer." (PMID 39312285, 2024). "In a previous study in our laboratory, changes in many different DUSP proteins were observed after the induction of nonsmall cell lung cancer cells (A549) with TGFβ1, and a significant decrease in DUSP4 and DUSP13 was observed." (PMID 37476896, 2023). "At the RNA level, we observed that ALDOA coordinates with TRAF4 or DUSP4 in a TCGA lung cancer patient cohort." (PMID 32188842, 2020). "The top 10 proteins (MIG6, GAPDH, NDRG1_pT346, BRD4, CD26, TFRC, INPP4B, GSK3ALPHABETA, IGFBP2, and DUSP4) were screened by applying the WBFS algorithm, and they can be regarded as the candidate biomarkers that are most closely associated with the classification of lung cancer subtypes." (PMID 37509950, 2023). "The study found six promising protein biomarkers that were directly correlated with the classification of lung cancer subtypes, including MIG6, NDRG1_pT346, BRD4, CD26, INPP4B, and DUSP4." (PMID 37509950, 2023). "Of these, genes such as DUSP4 and AKT3 are well documented as being involved in smoking-related lung cancer." (PMID 28500316, 2017). "Clinical data from several available cohorts, including TCGA and meta-base 1000 patients with lung cancer, indicated that the ALDOA-Oct4-TRAF4/DUSP4 axis is a potential prognostic indicator and may be a therapeutic target." (PMID 32188842, 2020). "Furthermore, by combining those genes into a significant prognostic factor for lung cancer patients, we determined that ALDOA, together with TRAF4 or DUSP4, serves as an independent factor for the meta-base and TCGA lung cancer patient cohorts." (PMID 32188842, 2020). "Finally, we demonstrated a model in which ALDOA coordinates with DUSP4/TRAF4 and is correlated with a poor prognosis in lung cancer patients." (PMID 32188842, 2020). "In addition, deregulation of DUSP4 activity contributes to sustaining ERK signaling, resulting in oncogenic transformation in lung cancer cells." (PMID 25027955, 2014). "DUSP4, which belongs to dual-specificity phosphatase (DUSPs) family, regulating the activity and location of MAPKs, is a negative regulator of extracellular-regulated kinase activity and is upregulated in EGFR-mutant lung cancer cell lines compared with K-ras-mutant cells." (PMID 28500316, 2017).
cardiomyopathy (7 papers, 2014 to 2022). A disease of the heart muscle or myocardium proper. "The role of DUSP1 in protecting the heart from cardiomyopathy by inhibiting the MAPK effectors was shown in the Dusp1/Dusp4 double-knockout mouse model." (PMID 35625658, 2022). "Depletions of different DUSPs in mice have shown changes in cardiomyocyte morphology (DUSP8,), or have been linked to protection (DUSP6,) or, in contrast, to increased susceptibility to cardiomyopathy (DUSP1, DUSP4,)." (PMID 36227898, 2022). "DUSP4 is considered a protective target in cardiomyopathy and other CVDs." (PMID 35628106, 2022). "Coming from a fairly large family with 25 members, it is conceivable that different DUSPs may have overlapping functions, a possibility that is supported by a recent report showing that concomitant deletions of DUSP1 and DUSP4 are required for the induction of cardiomyopathy." (PMID 26710253, 2015). "DUSP4 and DUSP5 can be transcriptionally induced by ERK1/2, which suggests the possibility of ERK1/2 pathway activation in LMNA cardiomyopathy progression." (PMID 32313136, 2020). "Support for functional redundancy amongst the nuclear DUSPs comes from the recent report showing that in contrast to mice lacking either DUSP1 or DUSP4, which exhibit no cardiac pathology, mice missing both of these DUSPs develop cardiomyopathy due to unrestrained p38 activation." (PMID 25375135, 2014).
hepatocellular carcinoma (7 papers, 2012 to 2025). A malignant tumor that arises from hepatocytes. "DUSP4 suppresses ferroptosis in hepatocellular carcinoma by regulating ferritin mRNA localization through YTHDC1 phosphorylation, contributing to sorafenib resistance." (PMID 39315094, 2024). "Dual-specificity phosphatase 4 (DUSP4) inhibits sorafenib-induced ferroptosis in hepatocellular carcinoma by activating the RNA m6A reader, YTH N6-methyladenosine RNA binding protein C1 (YTHDC1), leading to enhanced expression of FTH and FTL." (PMID 39624080, 2024). "Moreover, dual specificity phosphatase 4 (DUSP4) as a negative regulator of sorafenib‐induced ferroptosis in hepatocellular carcinoma (HCC) modulated key ferroptosis‐related markers and possessed potential therapeutic strategies for overcoming sorafenib resistance." (PMID 40982354, 2025). "Likewise, the newly identified interaction between mir-122-5p and DUSP2 should be the subject of future studies since a significant negative correlation was found in hepatocellular carcinoma while miR-122-5p is primarily regarded as a liver-specific tumour suppressor i.a. by downregulation of DUSP4." (PMID 40537745, 2025).
lung adenocarcinoma (7 papers, 2014 to 2026). A carcinoma that arises from the lung and is characterized by the presence of malignant glandular epithelial cells. "Network structural analysis provided a comprehensive view of the complex miRNA–mRNA interactions in EGFR-mutated lung adenocarcinoma, including DUSP4 and MUC4 axes." (PMID 30404194, 2018). "In contrast, activating EGFR-mutation was related to downregulation of DUSP4 in lung adenocarcinomas, and in vitro knockdown of DUSP4 increased cell proliferation." (PMID 29100381, 2017). "Similarly, our mRNA expression signature in EGFR-mutated tumors included DUSP4, EGFR, TNFRSF10B, and LRRC3, all reportedly deregulated in EGFR-mutated lung adenocarcinoma." (PMID 30404194, 2018).
glioblastoma (6 papers, 2015 to 2023). The most malignant astrocytic tumor (WHO grade IV). "A literature review identified DUSP4, HIF-1α, and COL8A2 as being linked to ERK signaling, and analysis of a published dataset of chromatin immunoprecipitation sequencing (ChIP-seq) data for Bmi1 in neural stem cells and glioblastoma cells identified Dusp4 as a direct Bmi1 target gene." (PMID 29212025, 2017). "Furthermore, exogenous overexpression of DUSP4 has been shown to inhibit glioblastoma cell growth, indicating DUSP4 as a possible tumor suppressor." (PMID 25929337, 2015).
pancreatic cancer (6 papers, 2015 to 2023). "The protein interaction networks indicated a marked association of DUSP4 in anti-proliferative effects of sanguinarine in pancreatic cancer cells." (PMID 25929337, 2015). "Moreover, DUSP4 loss increased invasiveness in pancreatic cancer, and restoration of DUSP4 expression reversed this effect." (PMID 37946160, 2023). "The other role of DUSP4 in cancer is MAPK pathway inhibitor, and DUSP4 inhibition can cause the activation of ERK pathway which is involved in tumor invasiveness and drug resistance in breast and pancreatic cancer." (PMID 36127345, 2022). "Our proteomics data followed by qRT-PCR and immunoblot analysis demonstrated that sanguinarine significantly increases DUSP4 in pancreatic cancer BxPC-3 and MIA PaCa-2 cells." (PMID 25929337, 2015). "Our study suggests that DUSP4 is an important central hub, which interacts with several important molecules modulated by sanguinarine in pancreatic cancer." (PMID 25929337, 2015). "Some studies show that DUSP4 is significantly up‐regulated by sanguinarine in pancreatic cancer cells, suggesting that sanguinarine may act as the DUSP4 activator exerting its activity in cancer." (PMID 27957827, 2017). "The role of DUSP4 in pancreatic cancer has not yet been explored; however, an association of DUSP4 loss with cancer progression has been shown in certain cancers." (PMID 25929337, 2015).
colon carcinoma (5 papers, 2013 to 2025). "The results showed the enrichment of ASCL2 in colon cancer tissue is higher, while enrichment of DUSP4 is lower." (PMID 35774798, 2022). "The results of the IC50 values indicated a significant increase in the drug sensitivity of both ASCL2-LOW and DUSP4-HIGH to WNT pathway inhibitor in colon cancer." (PMID 35774798, 2022). "There were significant positive correlation between COX-2 expression levels and DUSP4 gene expression (r = 0.851, P < 0.001) and also between COX-2 and TROP2 expression levels (r = 0.866, P < 0.001) in all colon cancer tissues." (PMID 40328989, 2025). "We performed GSEA comparing colon cancer samples with high expression and low expression of ASCL2 and DUSP4 using TCGA dataset to identify pathways correlated with ASCL2 and DUSP4." (PMID 35774798, 2022). "A recent study also reported that DUSP4/MKP-2 and DUSP5 are induced in response to oncogenic activation of the ERK pathway in colon cancer-derived cells, which correlates with nuclear accumulation of dephosphorylated ERK." (PMID 22812510, 2013).
diabetes (5 papers, 2022 to 2025). "Diabetes-induced dual specificity phosphatase 4 (DUSP4) decreases and increases p38 and c-JunN-terminal kinase (JNK) activity, as well as induces podocyte dysfunction." (PMID 36497173, 2022).
Obesity (5 papers, 2014 to 2023). Accumulation of substantial excess body fat. "Other genes in MAPK signaling that are not significant according to the gene scores (RPS6KA4, DUSP4, MAPKAPK5) have also been associated with obesity." (PMID 37860106, 2023). "Functional redundancy amongst the nuclear specific DUSPs, which in addition to DUSP2 include DUSP1, DUSP4 and DUSP5, may also be a contributing factor in DUSP2 not playing a unique role in obesity-associated WAT inflammation." (PMID 25375135, 2014).
Sepsis (5 papers, 2015 to 2022). Sepsis is defined as life-threatening organ dysfunction caused by a dysregulated host response to infection. "The analyses of DUSP4-deficient mice further show that DUSP4 is important for TGFβ-induced apoptosis, inflammatory cytokine secretion, susceptibility to sepsis shock, and resistance to Leishmania mexicana infection." (PMID 26710253, 2015). "Differences between DUSP4/MKP-2 and DUSP1/MKP-1 were further underlined in studies of the response of DUSP4−/− mice to experimental LPS-induced sepsis." (PMID 30401534, 2019). "Two murine sepsis models revealed that DUSP4 is a positive regulator of inflammation, in contrast to the closely related DUSP1/MKP-1." (PMID 31159473, 2019). "As these results indicate an indirect phenotypic effect of the DUSP4 knockout, the combined deletion of both DUSP1 and DUSP4 is desirable to study DUSP redundancy and combinatorial effects during sepsis and inflammation." (PMID 31159473, 2019). "Here, Dusp4−/− mice showed improved survival in the high-dose LPS and the cecal ligation and puncture (CLP) model of sepsis, with attenuated levels of systemic IL-1β, IL-6 and TNF." (PMID 31159473, 2019).
Alzheimer disease (4 papers, 2015 to 2024). A progressive, neurodegenerative disease characterized by loss of function and death of nerve cells in several areas of the brain leading to loss of cognitive function such as memory and language. "Intriguingly, transcriptomic profiling of hippocampal RNAs in patients with Alzheimer’s disease (AD) showed a downregulation of DUSP4, suggesting a potential role for DUSP4 in AD-associated pathogenesis." (PMID 38254666, 2024). "DUSP4 is a member of the DUSP (Dual-Specificity Phosphatase) subfamily that is selective to the mitogen-activated protein kinases (MAPK) and has been implicated in a range of biological processes and functions in Alzheimer's disease (AD)." (PMID 37886598, 2023). "Indeed, the level of DUSP4 was reported to be downregulated in the postmortem brains of Alzheimer’s disease (AD) subjects, and previous network analyses identified DUSP4 as a hub gene in a major depressive disorder (MDD) female-specific module, which resulted in ERK activation." (PMID 36497141, 2022). "Importantly, DUSP4 gene expression, like that of VGF, is downregulated in postmortem Alzheimer’s disease (AD) brains." (PMID 36497141, 2022).
amyloid (4 papers, 2022 to 2024). "At 4 months of age, female 5xFAD mice showed a significant decrease in hippocampal Dusp4, Vgf and Bdnf expression, consistent with the well-documented increased severity of amyloid neuropathology at this age in females compared to males." (PMID 36497141, 2022). "DUSP-4 deletion in mice impairs cognition and memory and overexpressing DUSP4 reduced amyloid plaque burden in the hippocampi of 5XFAD AD mice brains." (PMID 37469955, 2023).
breast tumor (4 papers, 2020 to 2024). "DUSP4 is frequently deleted in breast tumours and cancer cell lines." (PMID 31936698, 2020).
head and neck squamous cell carcinoma (4 papers, 2014 to 2018). A squamous cell carcinoma that arises from any of the following anatomic sites: lip and oral cavity, nasal cavity, paranasal sinuses, pharynx, larynx, and salivary glands. "In addition, G9a inhibition induces autophagy in head and neck squamous cell carcinoma via epigenetically increasing dual specificity phosphatase-4 (DUSP4) to inactivate ERK." (PMID 26397365, 2015).
Insulin resistance (4 papers, 2015 to 2025). Increased resistance towards insulin, that is, diminished effectiveness of insulin in reducing blood glucose levels. "To further evaluate the role of DUSP4 in GC-induced insulin resistance, we infected WT mice with AAV8 expressing scramble shRNA (AAV8-Scr) or shRNA targeting Dusp4 (AAV8-shDusp4)." (PMID 37253782, 2023). "DUSP4 overexpression, however, did not affect Dex-induced insulin resistance." (PMID 37253782, 2023).
neuroblastoma (4 papers, 2018 to 2024). Neuroblastoma (NB) is the most common solid, extracranial childhood tumor. "Moreover, neuroblastoma-infiltrating T cells, particularly DUSP4+ CD4 T cells and CD8 T cells, displayed active downstream TIGIT and PD-1 signaling." (PMID 38181797, 2024).
ovarian carcinoma (4 papers, 2013 to 2023). A malignant neoplasm originating from the surface ovarian epithelium. "Previous studies focused on the potential use of DUSP1, DUSP4, and DUSP6 as diagnostic markers in ovarian cancer." (PMID 37476896, 2023). "Only three out of ten MPAS genes (PHLDA1, EPHA2, and DUSP4) displayed reproducible associations with baseline levels and changes in MEK/ERK activity across most ovarian cancer model systems and clinical samples." (PMID 36362153, 2022). "Levels of PHLDA1, DUSP4, and EPHA2 expression were also significantly associated with baseline levels of MEK/ERK pathway activity in multiple human ovarian cancer cell lines and ovarian cancer patient samples available from the TCGA database." (PMID 36362153, 2022). "Microarray analysis identified the downregulation of DUSP4, a known inhibitor of ERK, in serous ovarian carcinomas, in contrast to ovarian serous borderline tumors, suggesting a potential tool in ovarian cancer diagnosis and patient management." (PMID 37476896, 2023). "Only 3 of 10 MPAS genes (PHLDA1, DUSP4, and EPHA2) reflect MEK/ERK pathway activity significantly and consistently across multiple experimental models and clinical tissue samples of ovarian cancer." (PMID 36362153, 2022). "We evaluated possible associations between the expression of PHLDA1, SPRY4, EPHA2, and DUSP4 and MEK/ERK pathway activity in 20 ovarian cancer cell lines." (PMID 36362153, 2022).
myocardial infarction (3 papers, 2019 to 2022). Gross necrosis of the myocardium, as a result of interruption of the blood supply to the area, as in coronary thrombosis. "By modulating p38 kinase activity, DUSP4 is considered a good target for the treatment of myocardial infarction." (PMID 35628106, 2022). "We identified several potential loci, in particular PHLPP2, BBS9, RyR2, DUSP4 and HSPA8, associated with new-onset of atrial fibrillation, delirium, myocardial infarction, acute kidney injury and stroke after cardiac surgery." (PMID 30678657, 2019). "And we employed a well-accepted myocardial infarction (MI) injury model and investigate on the role of HDAC1 in DUSP4/p38 pathway using HDAC1 siRNA in fibroblasts isolated from neonatal mice." (PMID 34236463, 2022).
papillary thyroid carcinoma (3 papers, 2018 to 2024). "Meanwhile, DUSP4/MKP2 overexpression is also associated with the aggressive behavior of BRAF V600E-mutated papillary thyroid cancer." (PMID 30111351, 2018). "In a study on papillary thyroid carcinoma, high DUSP4 expression suggested a better clinical outcome." (PMID 34679636, 2021). "Furthermore, the TB-1 peptide inhibited the tumorigenesis of dual specificity phosphatase 4-positive papillary thyroid carcinoma cells." (PMID 39596437, 2024).
prostate carcinoma (3 papers, 2014 to 2017). A carcinoma that arises from epithelial cells of the prostate gland. "A recent report has shown that ETS1 knockdown in DU145 prostate cancer cells activates dual specificity phosphatase 4 (DUSP4), DUSP6, and sprouty RTK-signaling antagonist 4 (SPRY4)." (PMID 28474232, 2017).
renal cell carcinoma (3 papers, 2021 to 2023). "Loss of DUSP4 expression was noted in most histological subtypes of renal cell carcinoma." (PMID 34679636, 2021). "The prognostic impact of DUSP4 expression in renal cell carcinoma is not well studied." (PMID 34679636, 2021).